BPIFA3 (BPI fold containing family A member 3)
Synonyms: C20orf71; SPLUNC3; bA49G10.4
Tractability: Antibody: UniProt places it where antibodies can reach, with high confidence; UniProt predicts a signal peptide or a membrane-spanning region; its Gene Ontology location is reachable by antibodies, with medium confidence.
Gene: Protein-coding gene on chromosome 20 (33,217,310 to 33,227,806, forward strand). Ensembl gene ENSG00000131059.
Subcellular location: Secreted
Gene Ontology:
Molecular function: lipid binding
Cellular component: extracellular region
Genetic constraint (gnomAD): Loss-of-function variants: 33 observed, 29.18 expected, observed/expected ratio (o/e) 1.13, 90% interval 0.86 to 1.51. The upper end of that interval is the gene's LOEUF score, 1.51, which puts it in group 6 of 6, group 1 being the genes least tolerant of losing a copy. Missense variants: 315 observed, 314.88 expected, observed/expected ratio (o/e) 1, 90% interval 0.91 to 1.1. Synonymous variants: 110 observed, 118.44 expected, observed/expected ratio (o/e) 0.93, 90% interval 0.8 to 1.09.
Homologues: Orthologues: chimpanzee BPIFA3 (96% identical), macaque BPIFA3 (91% identical), dog BPIFA3 (62% identical), mouse Bpifa3 (61% identical), pig BPIFA3 (61% identical), rat Bpifa3 (56% identical), Caenorhabditis elegans C06E8.5 (11% identical). Paralogues in human: BPIFA1 (21% identical), BPIFB3 (19% identical), BPI (18% identical), BPIFB4 (18% identical), BPIFB1 (16% identical), LBP (16% identical), PLTP (15% identical), BPIFA2 (15% identical), BPIFC (14% identical), BPIFB6 (14% identical), CETP (13% identical), BPIFB2 (12% identical).
Diseases named in the same sentence as BPIFA3 in open-access papers:
BPIFA3 is named in the same sentence as 1 disease in open-access papers, as found by Europe PMC text mining. Sharing a sentence is not in itself a finding about the gene and the disease. The quoted sentences say what the papers report.
lung carcinoma (1 paper, 2015). "Whereas, other proteins, such as LPCAT2 that is highly expressed in inflammatory cells, BPIFA3 that is highly expressed in lung cancer, PPIA that activates NFkB pathway, and FABP4 that has pro-angiogenic role, were downregulated in SBP1 overexpression xenograft tumors." (PMID 25974208, 2015).